MMP24 (matrix metallopeptidase 24)
Description:
Metalloprotease that mediates cleavage of N-cadherin (CDH2) and acts as a regulator of neuro-immune interactions and neural stem cell quiescence. Involved in cell-cell interactions between nociceptive neurites and mast cells, possibly by mediating cleavage of CDH2, thereby acting as a mediator of peripheral thermal nociception and inflammatory hyperalgesia. Key regulator of neural stem cells quiescence by mediating cleavage of CDH2, affecting CDH2-mediated anchorage of neural stem cells to ependymocytes in the adult subependymal zone, leading to modulate their quiescence. May play a role in axonal growth. Able to activate progelatinase A. May also be a proteoglycanase involved in degradation of proteoglycans, such as dermatan sulfate and chondroitin sulfate proteoglycans. Cleaves partially fibronectin, but not collagen type I, nor laminin (By similarity).
Synonyms: MMP-24; MT-MMP 5; MTMMP5; MT5-MMP; MT5MMP; MMP25; MT-MMP5
Tractability: Small molecule: it belongs to a druggable protein family. Antibody: its Gene Ontology location is reachable by antibodies, with high confidence; UniProt places it where antibodies can reach, with medium confidence; UniProt predicts a signal peptide or a membrane-spanning region; the Human Protein Atlas places it where antibodies can reach. PROTAC: its protein half-life has been measured; a small molecule that binds it is known.
Target class: Metallo protease; Metallo protease M10A subfamily; Metallo protease MAM clan; Protease; Enzyme
Gene: Protein-coding gene on chromosome 20 (35,226,559 to 35,276,998, forward strand). Ensembl gene ENSG00000125966.
Subcellular location: Cell membrane (Matrix metalloproteinase-24); Golgi apparatus, trans-Golgi network membrane; Secreted, extracellular space, extracellular matrix (Processed matrix metalloproteinase-24)
Subcellular location (Human Protein Atlas): Nucleoli; Plasma membrane; Predicted to be secreted
Pathways (Reactome):
Extracellular matrix organization: Activation of Matrix Metalloproteinases
Gene Ontology:
Molecular function: protein binding; enzyme activator activity; metalloendopeptidase activity; cadherin binding; metallopeptidase activity; zinc ion binding
Biological process: cell-cell adhesion; cell-cell adhesion mediated by cadherin; collagen catabolic process; detection of temperature stimulus involved in sensory perception of pain; extracellular matrix organization; glial cell differentiation; neuronal stem cell population maintenance; proteolysis
Cellular component: extracellular exosome; plasma membrane; trans-Golgi network membrane; extracellular matrix; Golgi apparatus
Genetic constraint (gnomAD): Loss-of-function variants: 25 observed, 58.64 expected, observed/expected ratio (o/e) 0.43, 90% interval 0.31 to 0.6. The upper end of that interval is the gene's LOEUF score, 0.6, which puts it in group 2 of 6, group 1 being the genes least tolerant of losing a copy. Missense variants: 611 observed, 813.24 expected, observed/expected ratio (o/e) 0.75, 90% interval 0.7 to 0.8. Synonymous variants: 312 observed, 326.93 expected, observed/expected ratio (o/e) 0.95, 90% interval 0.87 to 1.05.
Homologues: Orthologues: chimpanzee MMP24 (100% identical), macaque MMP24 (97% identical), dog MMP24 (97% identical), pig MMP24 (95% identical), rat Mmp24 (91% identical), mouse Mmp24 (91% identical), rabbit MMP24 (88% identical), guinea pig MMP24 (87% identical), tropical clawed frog mmp24 (78% identical), zebrafish mmp24 (74% identical), Caenorhabditis elegans zmp-3 (24% identical), Caenorhabditis elegans zmp-4 (17% identical), and 3 more. Paralogues in human: MMP16 (62% identical), MMP15 (51% identical), MMP14 (49% identical), MMP25 (30% identical), MMP17 (29% identical), MMP1 (29% identical), MMP12 (29% identical), MMP3 (29% identical), MMP2 (28% identical), MMP8 (28% identical), MMP11 (28% identical), MMP27 (28% identical), and 11 more.
Diseases named in the same sentence as MMP24 in open-access papers:
MMP24 is named in the same sentence as 50 diseases in open-access papers, as found by Europe PMC text mining. Sharing a sentence is not in itself a finding about the gene and the disease. The quoted sentences say what the papers report.
breast carcinoma (12 papers, 2009 to 2025). "MMP24 is a gene encoding matrix metalloproteinase-24 and has recently been reported to negatively regulate the aggressiveness of cancer cells in breast cancer as a target gene of yes-associated protein (YAP)." (PMID 32906679, 2020). "Prior studies have shown that when REST is knocked down in breast cancer cells, MMP24 is overexpressed by RNA sequencing." (PMID 39273639, 2024). "CEMIP and MMP24 have been previously shown to be upregulated in breast cancer patient samples and cell lines." (PMID 35177031, 2022). "Unfortunately, little is known about the role of MMP24 in breast cancer and what factors contribute to its regulation." (PMID 35177031, 2022). "It has been shown that miR-6775-3p can negatively regulate CDK4, CDK6, MMP17, and MMP24 levels in breast cancer cells by binding to the 3′UTR of their mRNAs, thereby inhibiting the proliferation, migration, and invasive abilities of breast cancer cells." (PMID 35891968, 2022). "Based on previous studies, it is likely REST is regulating MMP24 expression in breast cancer patient samples." (PMID 35177031, 2022). "Based on the Human Protein Atlas database, breast cancer patients with lower MMP24 expression exhibit the worse survival rates overall." (PMID 32093160, 2020). "We first examined the effect of substrate stiffness on MMP24 expression in MCF-7 human breast cancer cells and showed that the expression of MMP24 was significantly higher in cells grown on stiff substrates than that on soft substrates." (PMID 32093160, 2020). "The result showed that breast cancer patients with lower levels of MMP24 expression exhibit worse survival rates overall." (PMID 32093160, 2020). "Activation of YAP-TEAD then promotes the expression of MMP24, retarding the progression of various types of cancers such as breast cancer, lung cancer, and renal cancer." (PMID 32093160, 2020). "Abnormal methylation of MMP24 and MMP25 was significantly associated with a CpG island hypermethylated breast cancer subtype discovered by genome-wide DNA bisulfite sequencing." (PMID 32397602, 2020). "We also compared the expression intensities of PRSS23, CTSC, CTSF, and MMP-24 from 52 ERα-positive breast cancer specimens within the van't Veer dataset." (PMID 22291950, 2012). "For another membrane bound MMP, MMP-24, only the size of the latent protein was known and its expression was found to be significantly higher in breast cancer tissue." (PMID 19531263, 2009). "In contrast, DCBLD2 and MMP24 showed significantly higher expression ratios in the solid tumours in comparison with the breast cancer cell lines." (PMID 19615061, 2009). "We wanted to confirm that REST directly regulates MMP24 in breast cancer cells." (PMID 35177031, 2022). "Therefore, further studies are needed to clarify how CEMIP and MMP24 are regulated in breast cancer." (PMID 35177031, 2022). "While the loss of REST has previously been shown to increase MMP24 expression in breast cancer cells, transcriptional regulation of MMP24 by REST has not been studied so far." (PMID 35177031, 2022). "Studies in breast cancer, endometriosis, and lung cancer have all shown MMP24 overexpression." (PMID 35177031, 2022). "However, additional studies are needed to determine the exact roles CEMIP and MMP24 overexpression play in breast cancer." (PMID 35177031, 2022). "Breast cancer patients with lower MMP24 expression show lower survival rates." (PMID 32093160, 2020). "However, little is known about the role of MMP24 in cancer—particularly breast cancer." (PMID 32093160, 2020). "While the elastic modulus of tumor ECM is correlated with the aggressiveness of cancer cells, these results imply that in cancers such as breast cancer, lung cancer, pancreatic cancer, and renal cancer, MMP24 may retard tumor progression under the stiff environment of the cancer niche." (PMID 32093160, 2020). "We wondered whether rigid substrates also promote MMP24 expression in breast cancer cells." (PMID 32093160, 2020).
breast carcinoma (continued). "REST knockdown in breast cancer cells leads to the significant upregulation of KIAA1199/CEMIP (cell migration-inducing, hyaluronan-binding protein) and MMP24 (matrix metallopeptidase 24), genes which are involved in cell invasion and metastasis." (PMID 40006989, 2025). "By MSRE-PCR, we identified abnormal hypermethylation of promoter CpG dinucleotides of five MMP genes, MMP2, MMP23B, MMP24, MMP25, and MMP28, in breast cancer." (PMID 32397602, 2020). "In our collection of 183 breast cancer samples, abnormal hypermethylation was observed for CpGs in MMP2, MMP23B, MMP24, MMP25, and MMP28 promoter regions." (PMID 32397602, 2020). "Additionally, in breast cancer, a regulatory role of REST on MMP24 expression, a gene that is increased in PCa, has been proposed." (PMID 38542313, 2024). "REST knockdown in breast cancer cells leads to significant upregulation of CEMIP and MMP24." (PMID 35177031, 2022). "The 3 pairs, corresponding to discoidin, CUB and LCCL domain containing 2 (DCBLD2, NM_080927.3), matrix metallopeptidase 24 (MMP24, NM_006690.3) and keratin 81 (KRT81, NM_002281.3) had their expression interrogated in 16 breast cancer cell lines and ten solid primary breast tumours." (PMID 19615061, 2009). "MMP24 expression that has been identified as a YAP-TEAD target gene in this study is believed to attenuate cancer progression, since high MMP24 expression reflects prolonged overall survival rate of patients with cancers such as breast cancer, lung cancer, pancreatic cancer, and renal cancer." (PMID 32093160, 2020). "While differential expression of the sense and antisense transcript for MMP24 was more prominent in luminal breast cancer cell lines (3/5), significant different expression levels of the DCBLD2 -SAS pair were observed solely in two luminal, hormone receptor positive breast cancer cell lines." (PMID 19615061, 2009). "In contrast to MMP24, higher levels of MMP7 expression were associated with lower survival rates in patients with lung cancer, pancreatic cancer, or renal cancer but not colorectal cancer, whereas MMP7 was not a prognostic factor for breast cancer in the Human Protein Atlas database." (PMID 32093160, 2020). "Future directions for determining the functional roles CEMIP and MMP24 play in breast cancer pathogenesis and metastasis will include invasion and migration assays in the presence and absence of REST, CEMIP and MMP24." (PMID 35177031, 2022).
lung carcinoma (7 papers, 2017 to 2024). "According to recent publications, MMP24 (ENSP00000246186) is associated with lung cancer at different omics levels." (PMID 35155435, 2022). "At genomics and post-transcriptomics levels, variants on MMP24 have been shown to be associated with lung cancer via a GWAS study in 2015." (PMID 35155435, 2022). "In 2019, researchers from Tumor Hospital of Wuwei confirmed that microRNA-133a regulates MMP24 and further contributes to the tumorigenesis of lung cancer." (PMID 35155435, 2022). "MMP24 promotes neuronal migration, contributes to Alzheimer’s pathogenesis and is necessary for lung cancer invasion and metastasis." (PMID 35177031, 2022). "Further investigations revealed that also in other cancers including lung cancer, pancreatic cancer, and renal cancer, patients with lower levels of MMP24 expression exhibit lower overall survival rates." (PMID 32093160, 2020). "Several genes, such as HOXC12, HAND1, VIPR2, KRT20, MMP24, and VIPR2, were discovered, and their special roles at different omics levels of lung cancer were confirmed." (PMID 35155435, 2022). "In our study, we found that miR‐558 has binding sites for MMP1, MMP16, MMP17, and MMP24 3'‐UTRs, and only MMP17 and MMP1 were demonstrated to be significantly downregulated by miR‐558 through targeted regulation in lung cancer cells." (PMID 33190405, 2021). "In this study, we also showed that in contrast to MMP24, high expression of MMP7, which is another YAP-TEAD target gene, is associated with poor prognosis in lung cancer, pancreatic cancer, and renal cancer but not colorectal cancer." (PMID 32093160, 2020).
Alzheimer disease (4 papers, 2019 to 2024). A progressive, neurodegenerative disease characterized by loss of function and death of nerve cells in several areas of the brain leading to loss of cognitive function such as memory and language. "MMP24 is dominantly expressed in neuronal cells and the function of MMP24 in Alzheimer’s disease has been well studied." (PMID 32093160, 2020).
ovarian carcinoma (4 papers, 2010 to 2025). A malignant neoplasm originating from the surface ovarian epithelium. "A strong expression of the mRNA and protein (approximately 65 KDa and 55 KDa) of MMP-24 was found in the ovarian carcinoma derived BG1 cells." (PMID 20942921, 2010).
glioma (3 papers, 2020 to 2024). A benign or malignant brain and spinal cord tumor that arises from glial cells (astrocytes, oligodendrocytes, ependymal cells). "In a previous study on glioma, the expression of MMP24 was high in brain tumors and was reportedly to related to tumor progression, but the available data for MMP24 in later study seemed to be contradictory." (PMID 32906679, 2020). "Elevated MMP24 expression worsens prognosis in glioma, oligodendroglioma, and meningioma patients." (PMID 39022728, 2024). "For these reasons, further studies on MMP24 in glioma are needed." (PMID 32906679, 2020). "Possibly correlating with the very low RNA expression levels observed, MMP15 and MMP24 were not detectable by immunohistochemistry in glioma tissue." (PMID 32872536, 2020).
endometriosis (2 papers, 2011 to 2019). The growth of functional endometrial tissue in anatomic sites outside the uterine body. "For instance, matrix metallopeptidase 24 (MMP24) is a predicted target for miR-941, and it facilitates tissue remodeling and cell migration in endometrium from endometriosis patients." (PMID 21698188, 2011). "Several studies have reported higher expression of MMP-2, MMP-9, MMP-14, and MMP-24 in the eutopic endometrium or ectopic lesions of women with endometriosis, as compared to levels in women without endometriosis." (PMID 31636643, 2019).
gastric cancer (2 papers, 2020 to 2024). A primary or metastatic malignant neoplasm involving the stomach. "We found that the MAP3K6 and MMP24 signal molecules were regulated by miR-1343-3p in gastric cancer cells, and miR-1343-3p was negatively correlated with the expression of these signal molecules." (PMID 38436092, 2024). "miR-1343-3p binds the target mRNA genes MAP3K6 and MMP24 in gastric cancer cells, and then suppresses the expression of MAP3K6 and MMP24, inhibiting the proliferation and invasion of cancer cells." (PMID 38436092, 2024). "In order to verify the expression of miR-1343-3p, MAP3K6, and MMP24 in gastric cancer cells after treatment with salidroside, we conducted quantitative PCR and immunostaining assay." (PMID 38436092, 2024). "Trever G Bivona also suggested that MMP24 was a biomarker of tumor progression and worse outcomes in lung and/or gastric cancer patients." (PMID 32850314, 2020). "Immunohistochemistry further clarified the expression of MAP3K6, MMP24, and STAT3 in gastric cancer cells after salidroside treatment." (PMID 38436092, 2024). "Our experimental results showed that salidroside promoted the expression of miR-1343-3p in gastric cancer cells and down-regulated the expression of MAP3K6 and MMP24 mRNA genes significantly." (PMID 38436092, 2024). "Salidroside is likely to suppress the growth of gastric cancer by up-regulating the tumor suppressor miR-1343-3p and down-regulating the expression of MAP3K6 and MMP24 signal molecules." (PMID 38436092, 2024). "Salidroside may suppress the growth of gastric cancer by up-regulating the expression of the tumor suppressor miR-1343-3p and down-regulating the expression of MAP3K6 and MMP24 signal molecules." (PMID 38436092, 2024).
oligodendroglioma (2 papers, 2020 to 2024). A well-differentiated (WHO grade II), diffusely infiltrating neuroglial tumor, typically located in the cerebral hemispheres. "Additionally, in the analysis of mutations in meningioma cells, heightened expression of metalloproteinase MMP24 was observed, a feature also present in oligodendrogliomas (OMIM 604871)." (PMID 39022728, 2024).
atherosclerosis (1 paper, 2020). A disease characterized by the build-up of fatty material and calcium deposition in the arterial wall resulting in partial or complete occlusion of the arterial lumen. "Here, we present the first reported association between MMP24 and atherosclerosis, although links with other MMPs in the MT-MMP subtype have been described before." (PMID 32206187, 2020). "Moreover, our blood results corroborate that MMP24 may play a role in atherosclerosis due to epigenetic modifications." (PMID 32206187, 2020). "While there is no previous literature linking our primary association, MMP24, with atherosclerosis, a vast catalog of studies on RNA expression, plasma levels studies, genetics and methylation in the MMP gene family corroborate the biopathological plausibility of its role in plaque progression." (PMID 32206187, 2020).
chordoma (1 paper, 2024). Chordomas are rare malignant tumors arising from embryonic remnants of the notochord in axial skeleton. "When Brachyury genes are highly expressed in human chordoma cells, matrix metalloproteinases (e.g. MMP12, MMP13 and MMP24; 74) are also upregulated at the same time (which is also seen in hypochordal cells)." (PMID 39191278, 2024).
Cirrhosis (1 paper, 2023). A chronic disorder of the liver in which liver tissue becomes scarred and is partially replaced by regenerative nodules and fibrotic tissue resulting in loss of liver function. "Most liver cells have high levels of MMP-2, -3, -7, and -16 during viral hepatitis and HCC; MMP-8, -9, -10-, -12, -13, -14, and MMP-16 during HCC and cirrhosis; and MMP-24 during liver regeneration." (PMID 37509493, 2023).
coagulopathy (1 paper, 2023). "In patients with trauma, succinate levels were associated with glycocalyx damage and the development of coagulopathy, and the interaction of MMP24 and syndecan-1 was elevated compared to healthy controls." (PMID 37315138, 2023).
colorectal cancer (1 paper, 2020). A primary or metastatic malignant neoplasm that affects the colon or rectum. "In contrast, although not statistically significant (p = 0.12), there was a tendency that colorectal cancer patients with higher levels of MMP24 expression exhibit lower survival rates." (PMID 32093160, 2020).
diabetic kidney disease (1 paper, 2025). Progressive kidney disorder caused by vascular damage to the glomerular capillaries, in patients with diabetes mellitus. "Pro-MMP-2 is converted into its active form by MMP-24, which is increased in the tubular epithelium in human diabetic kidney disease (DKD)." (PMID 40492135, 2025).
endometrial cancer (1 paper, 2024). Primary or metastatic malignant neoplasm involving the endometrium (mucous membrane that lines the endometrial cavity). "We analyzed the expression of REST and MMP24 in 31 cases of endometrial cancer and 16 controls." (PMID 39273639, 2024).
Endometrial Intraepithelial Neoplasia (1 paper, 2024). A premalignant neoplastic process that affects the endometrial epithelium and glands. "Exploring REST and MMP24 levels by immunostaining or RNA sequencing in either normal tissue adjacent to the tumor or in patients with endometrial intraepithelial neoplasia will also help determine the role of these markers in pre-cancerous tissue." (PMID 39273639, 2024).